CXCR4 (C-X-C motif chemokine receptor 4)
Diseases named in the same sentence as CXCR4 in open-access papers (continued):
Sharing a sentence is not in itself a finding about the gene and the disease.
bone tumor (continued). "Thus, to determine the role of PI4KA in CXCL12/CXCR4 signaling contributing to bone tumor growth, we have developed stable knockdown of PI4KA in PC3-CXCR4 and C4-2B cell with two independent PI4KA shRNA (#27 and #30) through lentiviral transduction." (PMID 37996444, 2023). "Since CXCR4 transactivates EGFR and HER2, we tested whether growth factor receptor signaling contributes to bone tumor growth." (PMID 27809841, 2016). "Bone colonizing PC-3 cells induce the expression of active MMP-9 at earlier time periods suggesting that CXCL12/CXCR4-mediated homing of PC cells to bone would functionally link with the expression of MMP-9 in local bone tumor microenvironment and induce invasive bone tumor growth." (PMID 24472670, 2014). "Moreover, the inhibition of SDF-1/CXCR-4 axis in metastatic PC3 cells using anti-CXCR4 monoclonal antibody (mAb) or CXCR4 antagonist, AMD3011 has been observed to impair their homing at the hypoxic endosteal niche in BM and inhibit bone tumour formation." (PMID 23301832, 2013). "CXCR4 and E-selectin antagonist may modify the composition of osteolytic behavior and this may be impacting bone tumor growth in the presence or absence of DTX and to be responsible for apparently “off-target effects”." (PMID 31877673, 2019).
endometriosis (22 papers, 2014 to 2025). The growth of functional endometrial tissue in anatomic sites outside the uterine body. "Both treatments may also exert activity by acting on endometriosis‐associated vasculature expressing CXCR4 and CXCR7." (PMID 31904910, 2020). "Loss of CXCR4, the receptor for CXCL12, in response to OCPs is also interesting, as this has been reported to reduce proliferation and lesion number in endometriosis." (PMID 38999962, 2024). "Using this model, we report for the first-time concurrent assessment of both Cd74 and Cxcr4 expression in endometriotic lesion tissue from mice with experimentally-induced endometriosis." (PMID 35885004, 2022). "In summary, using a reproductively intact, immune competent mouse model of experimental endometriosis, we report lesion expression of Mif receptors Cd74 and Cxcr4." (PMID 35885004, 2022). "With respect to endometriosis, CXCR4 transcript and protein is expressed in human endometriotic lesion tissue including deep-infiltrating lesions, but its association with CD74 has not been assessed in experimental models for endometriosis." (PMID 35885004, 2022). "The data obtained in this study provide further support for a role of Mif receptors, Cd74 and Cxcr4 in the pathophysiology of endometriosis." (PMID 35885004, 2022). "Elevated CXCR4 have been reported to promote the occurrence of endometriosis, suggested its relation to the regulation of ovary function." (PMID 35986230, 2022). "Using a mouse bone marrow transplantation model, we show that bone marrow‐derived cells engrafting endometriosis express CXCR4 and CXCR7." (PMID 31904910, 2020). "Additionally, CXCL12/CXCR4/CXCR7 recruit and facilitate stem cell homing from the circulation to the endometriosis, causing inflammation." (PMID 41009445, 2025). "Modulating the CXCL12/CXCR4 axis or inhibiting the hormonal factors that enhance stem cell migration could help prevent the development of endometriosis or reduce the growth of ectopic lesions." (PMID 41415877, 2025). "The expression of CXCR4 is enhanced by hormonal stimuli, notably progesterone and estrogen, highlighting the complex interaction between stem cells, the immune system, and the hormonal milieu in endometriosis." (PMID 41415877, 2025). "The data suggested that local CXCR4 expression might be required for the proliferation of the epithelial compartment in endometriosis lesions." (PMID 38933332, 2024). "An invention patent based on the use of CXCL12 (C-X-C Motif Chemokine Ligand 12) and/or CXCR4 (C-X-C motif chemokine receptor 4) levels as markers of TIAR for the early or preliminary stage and/or increased risk of adenomyosis or endometriosis was submitted by Dr. Leyendecker (WO 2019/106034)." (PMID 37371555, 2023). "CXCR4 is a chemokine receptor which is expressed in leukocytes, macrophages, and BM stem/progenitor cells and involved in immune cells or stem/progenitor cells chemotaxis in several inflammation conditions, including endometriosis." (PMID 37545483, 2023). "In contrast to Cd74, Cxcr4 mRNA expression slightly increased at 1 week from induction (1.43-fold increase, p = 0.093) with minimal increase (p < 0.05) from weeks 2- and 4-weeks post-endometriosis induction (week 0) in mice with WT lesions." (PMID 35885004, 2022). "A recent report by Tal and colleagues used Cxcr4-deficient tissue to establish experimentally-induced endometriosis and found that, compared to control lesions (which expressed Cxcr4), less lesions developed but development was not completely inhibited." (PMID 35885004, 2022). "The E2-CXCL12/CXCR4 signaling pathway may be useful in determining treatments for endometrial disorders, and may be antagonized to block stem cell migration to endometriosis." (PMID 25957946, 2015). "Notably, up to 30% of BMDCs in murine endometriosis expressed CXCR4, and 25% expressed CXCR7." (PMID 31904910, 2020). "Thus, EPHB4 may mediate the pathogenesis of endometriosis through SDF-1/CXCR4-driven angiogenesis." (PMID 40450304, 2025).
endometriosis (continued). "Genes involved in the initiation and regulation of autophagy (e.g., mTOR, CXCR4, and ESR1) are upregulated in endometriosis." (PMID 38645639, 2024). "CXCR4 is capable of forming dimers with MIF-bound CD74; however, the majority of the studies which have evaluated CXCR4 in the context of endometriosis have been evaluating it as a receptor for CXCL12." (PMID 35885004, 2022). "Targeting CXCR4 by using the small molecule receptor antagonist AMD3100 reduces the recruitment of BMDSCs into the endometriosis and the size of the endometriosis lesions." (PMID 34425902, 2021). "In human and mice models of endometriosis, higher levels of CXCL12 and CXCR4 were detected in ectopic lesions and serum than those in healthy controls." (PMID 34425902, 2021). "Suppressing the CXCL8 and CXCL12/CXCR4/CXCR7 axis prevents the development of inflammation in both PCOS and endometriosis, which may help to improve the prognosis of disorders associated with inflammation." (PMID 41009445, 2025). "The results indicated that the C1 SFRP2+ Fibroblast and C3 RAMP1+ Fibroblast subpopulations predominantly originated from the Endometriosis tissue type, while the C0 FHL2+ Fibroblast and C2 CXCR4+ Fibroblast subpopulations were mostly derived from the Endometriomas tissue type." (PMID 41159025, 2025). "Almost all of CECs originated from endometriosis rather than uterus express CXCR4 and MSCs biomarkers, but not hematopoietic stem cell markers, and contribute to both endometriosis and angiogenesis." (PMID 34425902, 2021). "Both CXCR4 and CXCR7 may represent new targets for regulating BMDCs engraftment into endometriosis with potential therapeutic applications." (PMID 31904910, 2020). "CXCR4 and CXCR7 antagonists are promising novel, non‐hormonal therapies for endometriosis." (PMID 31904910, 2020). "CXCR4 and CXCR7 antagonists are potential novel, non‐hormonal therapies for endometriosis." (PMID 31904910, 2020). "The high expression of CXCL12 in endometriosis and expression of CXCR4 and CXCR7 in BMDCs suggested that CXCL12 might serve to regulate BMDCs trafficking towards endometriosis." (PMID 31904910, 2020). "Regarding tissue type preference, the C0 FHL2+ Fibroblast and C2 CXCR4+ Fibroblast subpopulations were more common in Endometriomas, while the C3 RAMP1+ Fibroblast, C1 SFRP2+ Fibroblast, and C4 TFF3+ Fibroblast subpopulations were predominantly found in Endometriosis." (PMID 41159025, 2025). "Our results show that several mRNAs and pathways related to immune function, such as IL-1B, CXCR4, IL-7R, STAT4, CD14, and CCR5, as well as the FoxO signaling pathway, the Jak-STAT signaling pathway, and the NF-kappa B signaling pathway, have significant correlations with endometriosis." (PMID 38203209, 2023). "Similar to that observed in humans and a non-human primate model of endometriosis, Cd74 expression is elevated in lesion tissue in a temporal fashion while that of Cxcr4 shows minimal increase during initial lesion establishment but is reduced later during the lifespan." (PMID 35885004, 2022). "Given the central role of the CXCL12/CXCR4/CXCR7 axis on BMDCs trafficking and in the pathogenesis of endometriosis, we hypothesized that blocking CXCR4 or CXCR7 in endometriosis using a reproductive and immune‐competent murine model would inhibit the growth of endometriosis." (PMID 31904910, 2020). "Studies have found that CXCL12/CXCR4/CXCR7 axis mainly promotes the proliferation, migration, and invasion of endometriotic foci through mechanisms such as angiogenesis and induction of stem cell migration In endometriosis, and this process may be regulated by estradiol." (PMID 36524127, 2022).
ischemic stroke (22 papers, 2012 to 2026). A stroke disorder caused by obstruction of blood flow to the brain, due to thrombotic (local blood clot formation) or embolic (due to a blood clot or other material traveling from another site) event. "Dihydromyricetin inhibits injury caused by Ischemic stroke through the lncRNA SNHG17/miR-452-3p/CXCR4 axis." (PMID 39897488, 2025). "The precise expression of SDF‐1α and CXCR4 in ischemic stroke and the specific mechanism involved in remyelination require further exploration." (PMID 41355332, 2025). "In conclusion, our findings suggest that CCR5 and CXCR4 are promising targets for enhancing neuroplasticity post-ischemic stroke, thus providing potentially effective and reliable therapeutic targets for future interventional strategy." (PMID 40787669, 2025). "BBB-derived CXCL12/CXCR4 signaling promoted NK cell migration and improved functional outcomes after ischemic stroke in mice." (PMID 37817190, 2023). "Recent studies have demonstrated that CXCR4 is involved in the inflammatory response and exerts neuroprotective effects after ischemic stroke." (PMID 34795842, 2021). "CXCR4 is involved in regulating the inflammatory response in CNS diseases, such as Alzheimer's disease, ischemic stroke, and Parkinson's disease." (PMID 34795842, 2021). "Previous studies have indicated that CXCR4 antagonists reduced brain degeneration and improved behavioral recovery in the animals with ischemic stroke." (PMID 32992950, 2020). "The CXCL12/CXCR4 axis plays an important role in the treatment of ischemic stroke with transplanting BMSCs." (PMID 33381162, 2020). "Previous studies have indicated that CXCR4 antagonists reduced microglia activation, attenuated infiltration of T cells, and improved functional recovery in ischemic stroke animals." (PMID 32992950, 2020). "Firstly, we found that the expression of SDF-1α/CXCR4 axis is dysregulated in the brain of db/db diabetic mice at basal and in response to ischemic stroke." (PMID 23185548, 2012). "Our data demonstrate that CXCR4 over-expressing EPC further increases angiogenic repair following ischemic stroke." (PMID 23185548, 2012). "Furthermore, the expression levels of components of the SDF‐1α/CXCR4 axis influenced the effect of rTMS on ischemic stroke." (PMID 41355332, 2025). "Furthermore, some other studies have reported that CXCL-12/CXCR4 reduced neuronal apoptosis after traumatic brain injury and ischemic stroke." (PMID 34795842, 2021). "A common mechanism involving CXCR4 may contribute to neurodegeneration in hemorrhage and ischemic stroke." (PMID 32992950, 2020). "Here, we conducted in vivo studies to evaluate whether Ad-CXCR4 primed EPCs could enhance the benefits of EPC transfusion on treating ischemic stroke in the db/db diabetic mice." (PMID 23185548, 2012). "Furthermore, we tested the hypothesis that transfusion of Ad-CXCR4 primed EPCs is more effective on treating ischemic stroke in db/db mice." (PMID 23185548, 2012). "This research provides further evidence that 10 Hz rTMS can alleviate white matter injury in affected brain regions and improve PSCI after ischemic stroke, potentially through the activation of the SDF‐1α/CXCR4 axis." (PMID 41355332, 2025). "HIF‐1α silencing attenuates inflammation and oxidative stress in ischemic stroke male rats and oxygen‐glucose deprivation/reoxygenation (OGD/R) mice hippocampal cells via the CXCR4/NF‐κB pathway." (PMID 39295108, 2024). "Taken together, these findings suggest that SDF-1/CXCR4/CXCR7 signaling axis plays an important role in neurogenesis and angiogenesis after ischemic stroke." (PMID 29896417, 2018). "Stromal-derived factor-1 (SDF-1, also known as CXCL12) and its receptors CXCR4 and CXCR7 play important roles in brain repair after ischemic stroke, as SDF-1/ CXCR4/CXCR7 chemokine signaling is critical for recruiting stem cells to sites of ischemic injury." (PMID 29896417, 2018).
ischemic stroke (continued). "Furthermore, in a rat model of ischemic stroke, BMSCs combined with TMP promoted the homing of BMSCs towards ischemic areas by upregulating the expression of SDF-1 and CXCR4." (PMID 34490053, 2021). "Upregulation of SDF-1/CXCR4/CXCR7 chemokine signaling in the ischemic regions has been well-documented in the animal models of ischemic stroke, but not in human ischemic brain." (PMID 29896417, 2018). "Here, we found that protein expression of SDF-1 and CXCR7, but not CXCR4, were significantly increased in the cortical peri-infarct regions (penumbra) after ischemic stroke in human, compared with adjacent normal tissues and control subjects." (PMID 29896417, 2018). "The expression of SDF-1, CXCR7 and CXCR4 in neuron and astrocyte, these proteins were also expressed in the vascular cells in the brain of patients with ischemic stroke (data not shown)." (PMID 29896417, 2018). "In this study, we found that expression of SDF-1 and CXCR7, but not CXCR4, were significantly increased in the cortical peri-infarct regions after ischemic stroke, compared with adjacent normal tissues and control subjects." (PMID 29896417, 2018). "Our group has reported that overexpression of CXCR4 and ACE2 could enhance the beneficial effect of EPCs-based therapy for ischemic stroke by promoting EPC proliferation and survival." (PMID 27190523, 2016). "In a rat model of ischemic stroke, hypoxic preconditioning of bone marrow MSCs (BMSCs) improved their ability to promote cell homing, neuronal differentiation and regeneration, and the recovery of neuronal function via CXCL12/CXC chemokine receptor type 4 (CXCR4) signaling." (PMID 34490053, 2021). "The major finding of this study is that ischemic stroke in human leads to an increase in the expression of SDF-1 and CXCR7, but not CXCR4, in the peri-infarct cerebral cortex compared with the adjacent normal brain and ischemic core." (PMID 29896417, 2018). "Our data suggest that ischemic stroke in human leads to an increase in the expression of SDF-1 and CXCR7, but not CXCR4, in the peri-infarct cerebral cortex." (PMID 29896417, 2018).
metastatic carcinoma (22 papers, 2005 to 2025). A carcinoma which has spread from the original site of growth to another anatomic site. "As with almost all metastatic cancers, CXCR4 has been definitively identified as a key driver of metastatic melanoma." (PMID 39982274, 2025). "Metastatic carcinomas, which have undergone epithelial–mesenchymal transition, express CXCR4 in the nucleus." (PMID 38893721, 2024). "We also detected expression of CXCR4 on a number of other primary and/or metastatic cancers, including those of the breast, kidney, and lung." (PMID 29088715, 2017). "Based on these results and the published data on expression of CXCR4, we stained for CXCR4 on additional examples of a variety of primary and metastatic cancers." (PMID 29088715, 2017). "Overall, CXCR4 expression appeared to be greater in metastatic cancers, which was supported by comparisons using Fisher’s exact test." (PMID 29088715, 2017). "Most of the samples of metastatic cancers came from lymph nodes, and overall approximately 30% of cancer samples from lymph nodes were CXCR4+." (PMID 29088715, 2017). "CXCL12/CXCR4 has also been shown to play a key role in the regulation of metastasis, and its expression has been shown to be elevated in localized and metastatic cancer, including bone metastatic prostate tumors." (PMID 23902739, 2013). "Targeting SDF-1/CXCR4 signalling has been proposed for the prevention and treatment of metastatic carcinoma, specifically of the breast." (PMID 21087507, 2010). "Smith and colleagues found that CXCR4 inhibitors improve treatment of patients with primary and metastatic cancer." (PMID 19508713, 2009). "Recent evidence suggests that metastatic cancer cells overexpress CXCR4 and that this receptor plays a critical role in homing of cancer cells to specific metastatic sites." (PMID 18826577, 2008). "In diseases where excessive CXCR4 signaling exacerbates pathology, such as certain inflammatory and metastatic cancers, targeting GPR15LG could attenuate CXCL12-driven responses." (PMID 40394646, 2025). "Additionally, evidence of the CB2R heterodimerizing with the C-X-C Motif Chemokine Receptor 4 (CXCR4) has been observed in metastatic cancer cell lines, resulting in diminished functions of CXCR4 receptor and limited tumor cell migration and progression." (PMID 33080916, 2020). "SDF-1 further induced the occurrence of EMT in CD133+CXCR4+ cells, with a previous report demonstrating that inhibition of the SDF-1/CXCR4 axis could impede the invasive behavior of CXCR4-expressing cells in vitro and metastatic cancer formation in vivo." (PMID 22871210, 2012). "CXCR4 inhibitors are suggested for the treatment of different forms of metastatic cancer." (PMID 22693649, 2012). "The chemokine receptor CXCR4 and its cognate ligand, stromal cell-derived factor-1alpha (SDF-1), regulate cell trafficking in many different cell types including lymphocyte, mesenchymal stem cell as well as metastatic cancer cells." (PMID 21785640, 2011).